PTGS2 (prostaglandin-endoperoxide synthase 2)
Diseases named in the same sentence as PTGS2 in open-access papers (continued):
Sharing a sentence is not in itself a finding about the gene and the disease.
infection (122 papers, 2009 to 2026). The state of being infected such as from the introduction of a foreign agent such as serum, vaccine, antigenic substance or organism. "Prostaglandin-Endoperoxide Synthase 2 (PTGS2) is a key enzyme in prostaglandin biosynthesis associated with physiological stress, such as infection and inflammation." (PMID 39157338, 2024). "Infection with C. difficile suppressed colonic expression of the Ptgs1 and Ptgs2 genes, encoding COX-1 and COX-2, respectively." (PMID 30622186, 2019). "PTGS2 is involved in inflammatory processes such as infection, a potential risk factor for the disorder." (PMID 25941532, 2015). "Similarly, infection-induced Ptgs2 gene (encoding Cox-2) expression was enhanced in both sensitized and resolved differentiated urothelia relative to naïve." (PMID 37037942, 2023). "Among the differentially expressed genes, PTGS2 (COX-2) showed the highest level of upregulation in the infection group." (PMID 41937981, 2026). "The mRNA level of PTGS2 in the immunocompetent mice changed during the course of infection (H = 9.51, P = 0.009)." (PMID 40586570, 2025). "Among these, we focused on PTGS2, which showed a significant increase in mRNA expression at 2, 4, and 6 h post-infection (P < 0.01)." (PMID 40874199, 2025). "PTGS2 is an inducible enzyme that typically produces prostaglandin-like substances, which mediate responses to physiological stresses such as infection and inflammation." (PMID 40367136, 2025). "The expression of the PTGS2 protein, a pivotal biomarker for ferroptosis, was significantly increased in the infection group (p < 0.01)." (PMID 41343264, 2025). "PTGS2 can be induced to normally produce prostaglandins that regulate responses to physiological stress including infection and inflammation." (PMID 35747377, 2022). "The upregulation of Ptgs2 (the gene encoding cyclooxygenase 2) and Il6, typically associated with classical trained immunity, in BMDM of HDM-sensitized mice, suggests common features of trained immunity in infection and type 2 inflammation." (PMID 36065058, 2022). "Prostaglandin-endoperoxide synthase 2 (PTGS2) is a key enzyme involved in prostaglandin biosynthesis associated with physiological stresses, such as infection and inflammation." (PMID 35746681, 2022). "Four genes were differentially expressed in all four infection groups, of which expression of PTGS2, IL8 and CYP1A1 were upregulated, while expression of C9orf169 was upregulated at 2 h post infection, but downregulated at the 6 h time point." (PMID 37193047, 2022). "The literature suggests that expression of the COX2 encoding gene, PTGS2, is rapidly increased in primary monocyte-derived macrophages from MAP positive cows at 8 to 24 h post-infection." (PMID 36056402, 2022). "These included cytokines and cytokine receptors (Il11, Tnfsf18, and Ackr4), genes involved in infection (Ptgs2 and Heyl), cell adhesion and migration (Spon2 and Mmp10)." (PMID 35293863, 2022). "Several genes were significantly upregulated (Pla2g4a, Pla2g4c, Pla2g7, Ptgs1, Ptgs2, Pla1, Tbxas1) or downregulated (Alox5, Pla2g2d, Pla2g1b, Pla2g4b, Pla2g4f) during infection." (PMID 35812400, 2022). "The dynamics of Ptgs2 expression closely mirrored that of Tnf expression and differed with infection history." (PMID 31429405, 2019). "While Pla2g4a showed a moderate induction of log2FC = 2.9, expression of Ptgs2 was induced dramatically with log2FC = 11.5 at 4 h post infection, hinting at its importance during infection." (PMID 30669987, 2019). "P. aeruginosa markedly increased the expression of Ptgs2 mRNA in the lung of WT mice at 6 h after infection, whereas we observed significantly lower expression of Ptgs2 mRNA in infected IL-36R-/- mice and IL-36γ-/- mice." (PMID 29166668, 2017).
infection (continued). "In conclusion, the intradermal infection route is the most potent at inducing inflammatory genes expression and Ptgs2 seems to be a robust marker of Brucella intradermal infection compared to intranasal, conjunctival or oral infection routes." (PMID 28018318, 2016). "We next investigated the expression of Ptgs2 in murine GM-CSF-derived DC at 4, 8, 24, and 48 h post-infection." (PMID 28018318, 2016). "Overall, these results strongly suggest that in the CLN after intradermal infection a robust inflammatory response characterized by an Ifng and a Ptgs2 signature takes place." (PMID 28018318, 2016). "At the beginning of the chronic phase (29 days post-infection), we observed a strong decrease of Ifng, Il6, Gzmb concomitant with and an increase of Nos2, Ptgs2 mRNA levels." (PMID 28018318, 2016). "At 29 days post-infection, Ifng, Gzmb, and Il6 mRNA levels strongly decreased whereas a strong up-regulation of Ptgs2 and in a lesser extent Nos2 and Ccl2 mRNA levels remained." (PMID 28018318, 2016). "In immunocompetent mice, Ptgs2 and Ifng expressions were upregulated at the beginning of infection." (PMID 41828599, 2026). "Genes that were upregulated at all stages after infection, like Tnfa and Ptgs2, may be related to the maintenance of infectious inflammation." (PMID 38992966, 2025). "The PTGS2 gene is responsible for production of inflammatory prostaglandins and is specifically regulated during physiological stress, such as inflammation and infection." (PMID 39051372, 2024). "PTGS2 plays an important role in the infection process of many viruses." (PMID 38737277, 2024). "This indicates a clear suppression of male PTGS2 in response to the infection." (PMID 38879567, 2024). "Genes such as TNFα, IL10, TLR15, IL8L1 (CXCLi1), IL8L2 (CXCLi2), NOS2, ACOD1 and PTGS2 were upregulated with infection and microbiota, suggesting that macrophages may largely participate in the pro-inflammatory response described in caecal tissues." (PMID 38098020, 2023). "PTGS2 could activate the NF-κB signaling pathway which plays a key role in regulating the immune response to infection." (PMID 35012443, 2022). "As previously reported, PTGS2 is inducible and usually produces inflammatory prostaglandins, which mediate responses to physiological stress (infection and inflammation), stimulate chronic inflammation, and is a target for nonsteroidal anti-inflammatory drugs (NSAIDs)." (PMID 33927774, 2021). "We also noticed the elevated expression of ferroptosis biomarker Ptgs2 after MHV-A59 infection." (PMID 34960652, 2021). "In both BMDMs and BMDCs, infection with wild-type L. monocytogenes led to an increase in Ptgs2 expression and, to a lower extent, Ptges, suggesting that macrophages and dendritic cells could be capable of synthesizing PGE2." (PMID 34555127, 2021). "Consistent with this hypothesis, infection with this strain led to reduced Ptgs2 expression in BMDMs and BMDCs, suggesting that cytosolic access is required for optimal expression of Ptgs2." (PMID 34555127, 2021). "Confirming the observations made above, infection with all three L. major induces (cluster 1) neutrophil recruitment, myeloid activation, and production of cytokines/chemokines (e.g. Trem1, Trem3, C5ar1, Ltf, Ptgs2, Ccl2, Ccl12, Ccl17, etc.)." (PMID 34972189, 2021). "Thus, TLR4, IL27, and TNF were activated across all groups; IFNG was exclusively activated by AMTB-127 and AMTB-205; PTGS2 was activated in AMCTs and AMTBs in response to infection with Mtb UT205, whereas TLR2 was only activated in response to Mtb UT127." (PMID 32373118, 2020). "By comparing different infection routes (oral, intradermal, intranasal and conjunctival), we identified the intradermal inoculation route as the more potent in inducing Ptgs2 expression but also in inducing a local inflammatory response in the draining cervical lymph nodes (CLN)." (PMID 28018318, 2016). "We next investigated the involvement of the PTGS-2 pathway in vivo upon infection in mice." (PMID 28018318, 2016).
infection (continued). "Then, we determined the levels of expression of Ptgs2 in vivo using different infection routes." (PMID 28018318, 2016). "The expression of PTGS2 which codes for a prostaglandin dehydrogenase synthase, was highly induced in cells upon infection with Mtb (32-fold at 4 hr; 60-fold at 24 hr) and the complement (28-fold at 4 hr; 55-fold at 24 hr), relative to the mutant (4.8-fold at 4 hr; 45-fold at 24 hr)." (PMID 22235255, 2012). "At 24 h after infection, the following genes were upregulated in infected macrophages transfected with the let-7e inhibitor compared to macrophages transfected with NC: Tlr7, Ly96/MD-2, Casp8, Map3k1, Mapk8, Ptgs2/Cox2, Csf 3/GCSF, and the ubiquitin-conjugating enzyme E2N (Ube2n)." (PMID 30555476, 2018). "However, pharmacological inhibition of PG production, that is, inhibition of Ptgs1 and 2 or specifically Ptgs2, fully reversed the higher infection resistance of larvae forced to express Gbp4 but, unexpectedly, the resistance of larvae forced to express Asc was unaffected." (PMID 27363812, 2016). "In immunocompetent mice, we observed increased mRNA levels of interferon gamma (IFNγ), tumor necrosis factor alpha (TNFα), PTGS2/COX-2, and interleukin (IL)-17A at the beginning of infection." (PMID 40586570, 2025). "Differential expression analysis in this dataset showed a significant upregulation of four core genes (CCL5, PTGS2, HIF1A, and CLEC4E) in the infection group." (PMID 41039310, 2025). "Four genes previously thought to influence the severity of Guillan–Barré syndrome (GBS) were affected differently but moderately (PTGS2, Fc.: 1.188×; ANXA3, Fc.: 1.31×; CREB1, Fc.: 1.73×) by the 3rd hour of infection." (PMID 38787238, 2024). "In contrast, in AA-supplemented cultures from severe asthmatic donors, viral replication was enhanced whereas PTGS2 expression and PGE2 release were unchanged and CXCL8/IL-8 was significantly reduced in response to RV16 infection." (PMID 38179897, 2024). "Cultured primary human amnion fibroblasts, the major source of PGE2, were used to study the effects of bradykinin peptides on PTGS2 expression and PGE2 production as well as the effects of infection mediators on bradykinin receptors." (PMID 35634493, 2022). "Of these genes, SAA2 was the most significant (-10logp-value of 81); the distinctive genes in the SARS-CoV-2’s infection response were CSF3, CSF2, IL1B, and PTGS2." (PMID 33301474, 2020). "In this model, we also found that some genes exhibited a downward trend (e.g., Ptgs2, Rel, IL4r, CXCL1, CXCL2, TLR5, Nfatc3 and Egr2) in M. fortis after infection." (PMID 28900150, 2017). "However, some genes are down-regulated after stimulation, including IRF-1, a pivotal factor in the regulation of NK cells during infection, inflammation and metastasis, while PTGS2 is also down-regulated in NK cells, which could be favorable for NK function in SS." (PMID 29190907, 2017). "The list of genes with the greatest induction following Mtb:Δ-sigH infection at this time-point included CXCL1 (120-fold), PTGS2 (100-fold), CXCL6 (75-fold), CCL2 (53-fold), CXCL3 (40-fold), CXCL1 (43-fold) and CCL2 (38-fold) CCL5 (35-fold)." (PMID 22235255, 2012). "The RNA of Il6 and Ptgs2 detected by qPCR show similar trends to the transcriptome data, although the RNA of Tnfa and Il1b showed constant elevation post infection, which was not completely consistent with the transcriptome data." (PMID 38992966, 2025). "In contrast to responses of AA-supplemented PBEC cultures from non-asthmatic donors, RV16 infection did not affect expression of PTGS2 in cultures from severe asthmatic subjects and release of PGE2 was unchanged." (PMID 38179897, 2024). "Increased PTGS2 expression and subsequent prostaglandin E2 (PGE2) synthesis has been reported in the circulation and brain parenchyma of preterm humans and fetal sheep exposed to infection/inflammation." (PMID 38962513, 2024).
infection (continued). "However, IPA identified pro-inflammatory upstream regulators including PTGS2 (COX2), IL1A, and TNF that were activated after infection in aged mice." (PMID 35614490, 2022). "Additionally, RGS2 expression was strongly correlated with PTGS2, IL1B, CXCL8, NAMPT and other inflammation markers with substantial upregulation in early infection." (PMID 36143181, 2022). "Of note, upregulation of Ptgs2 expression and production of PGE2 were both potentiated by BMDM exposure to IFNγ prior to infection with Mtb, and the inhibitory effect of iFADS2 on Mtb-driven production of PGE2 production was maintained in IFNγ-activated macrophages." (PMID 34951591, 2021). "In contrast, in additional analysis, we showed that infection with UT127 could induce the expression of genes such as TNF, IL1B, and PTGS2, which together induce activation of apoptosis in MoCT but not in MoTB." (PMID 32391286, 2020). "Cluster 3 includes genes up-regulated exclusively by live parasites from 3 to 24h post infection which includes in particular, PLA2, Ptgs2 (COX-2) and Ptges while cluster 4 contains genes which transcription is more heavily up-regulated by KP across the kinetic of infection." (PMID 26871576, 2016). "The expression of PTGS2, a positive molecular marker of ferroptosis, were significantly increased after 3 hours of infection from the peripheral lavage fluid, indicating that ferroptosis occurs in the host after GBS infection, playing a positive role in the resolution of infection." (PMID 39353913, 2024). "Venn diagram analysis showed that among the common DGEs in the 3 h and 12 h infection groups compared with the control group, 11 differential genes were enriched in the NF-κB signaling pathway, including CXCL8, IL-1β, CCL4, IκBα, TNF, NF-κB, CFLAR, PTGS2, TRAF1, PLAU, and IL-1β2." (PMID 35215890, 2022). "The bradykinin system in human amnion may be involved in both term and preterm birth with or without infection through, at least in part, stimulation of PTGS2 expression and subsequent PGE2 production in amnion fibroblasts." (PMID 35634493, 2022). "This selective inhibition of Ptgs2 transcription, together with inhibition of Hpgd and enhancement of Ptges, is consistent with the paradoxical increase in PGE2 concentrations that we observed at 72 h after infection in the supernatant of colon explants from mice treated in the same manner." (PMID 30622186, 2019). "Furthermore, PTGS2 involved in the production of anti-inflammatory prostaglandins was also induced upon infection, with possible negative roles upstream and downstream of blocking IFN-STAT1-IRF activation pathways, while IRF2BP2 a potent repressor of innate inflammation was not." (PMID 28993767, 2017). "While not significantly upregulated following infection, transcription of ATF3, CXCL3, CXCL8, and PTGS2 was at least partially dependent on EGR1." (PMID 35746681, 2022).
cardiovascular disease (26 papers, 2005 to 2025). "It was reported that PTGS2 genetic variant, may be important risk factors for the development of cardiovascular disease events." (PMID 35422846, 2022). "The induction of disease by PTGS2 through mediating ferroptosis has been well reported in cardiovascular diseases." (PMID 40077919, 2025). "PTGS2 (Uniprot ID: P35355) was significantly upregulated by X‐ray treatment compared to the control group, while both KEGG map and GO analysis classified PTGS2 as a key target of acute inflammatory response in cardiovascular disease." (PMID 39494721, 2024). "PTGS2, prostaglandin-endoperoxide synthase 2, also known as COX2, is an enzyme involved in prostaglandin synthesis, which is associated with cardiovascular disease risk." (PMID 35422846, 2022). "NOS2 inhibitors and PTGS2 inhibitors have been identified for the treatment of cardiovascular disease." (PMID 34422068, 2021). "Notably, PTGS2 induces disease by mediating ferroptosis, which has been reported in cardiovascular diseases." (PMID 40077919, 2025). "So far, the role of PTGS2 in cardiovascular diseases remains controversial." (PMID 36523490, 2022). "In the pathological process of CVD, cardiovascular disease stimulates the expression of inflammatory cytokines, leading to the upregulation of inflammatory mediators such as PTGS-2, which promotes PTGS-2 gene to encode COX-2 protein, and finally resulting in vascular calcification." (PMID 34725557, 2021).
adenocarcinoma (21 papers, 2002 to 2025). A common cancer characterized by the presence of malignant glandular cells. "PTGS2 is more frequently expressed in adenocarcinomas than in SCCs (57–94% vs. 24%)." (PMID 35736434, 2022). "According to GSE29060 data, in HT-29 adenocarcinoma cells after a demethylation treatment 4 transcripts showed a minimally decreased expression (TIMP1, FADS1, CYP27B and SULT1A1), while PTGS2 was found to be upregulated." (PMID 26482433, 2015). "Furthermore, PTGS2 protein (COX-2, HUGO Gene Nomenclature Committee (HGNC): 9605) has been well studied as a mediator of CRC, with high expression noted in approximately 50% of adenomas and 85% of adenocarcinomas and is well correlated with poor patient prognosis." (PMID 40958118, 2025).
inflammation (18 papers, 2013 to 2025). Aberrant reaction of the microcirculation characterized by movement of fluid and leukocytes from the blood into extravascular tissues. "IL-10, IL-1β and COX-2 (encoded by IL10, IL1B, and PTGS2, respectively), are important mediators of intestinal inflammation." (PMID 24194923, 2013). "Besides, PTGS2 with the second highest degree played a critical role in the pathogenesis of gut inflammation." (PMID 31976001, 2019). "Furthermore, our studies demonstrate that proteases in poultry dust induce, in addition to IL-8 and IL-6, other genes implicated in lung inflammation such as IL-1β, CCL2, ICAM-1, PTGS2 and TLR4 in alveolar as well as bronchiolar epithelial cells." (PMID 27770804, 2016). "Extensive evidence supports a pivotal role of PTGS2 in gastric inflammation and carcinogenesis." (PMID 24901306, 2014).
neurodegenerative disease (18 papers, 2012 to 2025). A disorder of the central nervous system characterized by gradual and progressive loss of neural tissue and neurologic function. "The component-target-disease network diagram revealed that the essential oil compositions in leaves of C. grandis ‘Tomentosa’ could treat tumors, immune diseases, neurodegenerative diseases and respiratory diseases, which were highly related to CHRM1, PTGS2, CASP3, MAP2K1 and CDC25B." (PMID 35702766, 2023). "In the present study, JQ1 inhibited both Ptgs2 and Nos2 expression, and these inhibitory effects of JQ1 may play a potential role in the treatment of neurodegenerative diseases, possibly through its inhibition of microglia and the ensuing inflammatory responses in the CNS." (PMID 25890327, 2015).